SRF (serum response factor)
Diseases named in the same sentence as SRF in open-access papers (continued):
Sharing a sentence is not in itself a finding about the gene and the disease.
cardiac hypertrophy (38 papers, 2006 to 2025). "SRF can trigger the atrialnatriuretic factor, α-MHC, Acta 1, BNP, and β-MHC in isolated cardiomyocytes, which suggested that SRF is crucial to the regulation and induction of genes associated with the pathogenesis of pathologic cardiac hypertrophy." (PMID 36138345, 2022). "The muscle-specific miR-133 has critical functions in the heart and is a powerful inhibitor of cardiac hypertrophy and the transcription factor SRF is an important regulator of several hypertrophy associated genes, such as Nppa, Nppb and Acta1." (PMID 26919721, 2016). "Another TR associated with cardiac hypertrophy that was upregulated in our stimulated CMs is SRF." (PMID 35207580, 2022). "Both gain and loss of SRF function induce cardiac hypertrophy." (PMID 35185581, 2022). "SRF over-expression has been shown to cause cardiomyopathy and cardiac hypertrophy in mice." (PMID 29221435, 2017). "Hence, an unidentified link between cardiac hypertrophy and heart failure caused by overexpression of SRF may be involved, and the likely dependence of this missing link on NFAT signaling needs to be explored further." (PMID 35681202, 2022). "Histological examination showed increased cell size and large nuclei in the cardiomyocytes of SRF-Tg mice, thereby confirming cardiac hypertrophy." (PMID 40164849, 2025). "SRF in cardiomyocytes is involved in the induction of genes known to regulate cardiac hypertrophy and SRF overexpression in the heart results in pathological cardiac remodeling including cardiac hypertrophy." (PMID 39609264, 2025). "The expression of Myh14, a marker of isoproterenol‐mediated hypertrophy, and the transcription factor SRF, a known mediator of cardiac hypertrophy, was significantly increased in Iso‐treated cardiomyocytes as well as in the cardiomyocytes of old animals." (PMID 40538075, 2025). "Overall, our results revealed that cardiac-specific SRF overexpression exacerbated pathological cardiac hypertrophy and fibrosis." (PMID 40164849, 2025). "For example, circSlc8a1 has been found to alleviate cardiac hypertrophy by sequestering mir-133 and subsequently affecting the expression of serum response factor (Srf), connective tissue growth factor (Ctgf), and adrenergic receptor (Adrb1)." (PMID 39080192, 2024). "This resulted in the identification of KLF-4 interactions with genes like GATA4, MEF2C, TBX5, NKX2.5, and SRF, all of which are known regulators of cardiac hypertrophy and pro-hypertrophic pathways." (PMID 38672763, 2024). "Activated GATA4 is known to associate with other transcription factors such as serum response factor (SRF) and NK2 homeobox 5 (NKX2-5) to initiate the pathway for cardiac hypertrophy-related gene expression." (PMID 38255639, 2023). "Akt phosphorylation downregulates cardiac C/EBPβ, which de‐represses the transcription factors serum response factor (SRF) and CITED4 and subsequently enables transcription of genes encoding for proteins that are critical for physiological cardiac hypertrophy." (PMID 34957643, 2022). "As for mRNAs shown in the results of KEGG analysis of LINC00310, accumulated data have shown that KCNJ8 and SRF participate in the progression of pathologic cardiac hypertrophy." (PMID 36138345, 2022). "Transgenic mice with moderate cardiac-specific overexpression of the human SRF gene manifested significant cardiac hypertrophy and premature death." (PMID 36138345, 2022). "From mutant isoforms of SRF to overexpression or deletion of its interaction partners, SRF has been shown to play a role in a plethora of cardiovascular diseases, such as cardiac fibrosis, cardiac hypertrophy, hypertension and ultimately heart failure." (PMID 35681202, 2022). "SRF is known to be required for the induction of the “fetal gene program”, which is a set of genes that is characteristic of cardiac hypertrophy." (PMID 35207580, 2022). "SRF controls the expression of genes regulating the cytoskeleton during development and cardiac hypertrophy." (PMID 39802492, 2022).
cardiac hypertrophy (continued). "The homeo-domain-only protein (hopx) transgenic mice were recruited into chromatin to induce serum response factor (SRF)—dependent transcription and myocardial hypertrophy." (PMID 35127848, 2021). "In fact, a previous report showed that miR-133 regulates SRF and enhances muscle cell proliferation in mammals and another recent report showed that miR-133 promotes cardiac hypertrophy in zebrafish." (PMID 33663371, 2021). "MiR-133a can also attenuate cardiac hypertrophy by repressing the expression of serum response factor (SRF) and cyclin D2, both of which exacerbate aberrant cardiomyocyte proliferation and cardiac dysfunction." (PMID 31547607, 2019). "Studies showed that mice that overexpress miR-150 in the heart are resistant to cardiac hypertrophy through downregulation of serum response factor (SRF)." (PMID 29751665, 2018). "Additional studies showed that miR-22 represses a broad spectrum of target genes, including Sirt1, HDAC4, PPARα, and Purb, a negative regulator of Serum Response Factor (SRF) during the regulation of cardiac hypertrophy." (PMID 25153164, 2014). "Ablation of HOPX is sufficient to induce an up-regulation of some SRF target genes, and can lead to cardiac hypertrophy in mice." (PMID 23437181, 2013). "Heart-specific overexpression of SRF in transgenic mice led to the development of cardiac hypertrophy and cardiomyopathy, whereas overexpression of a mutant dominant-negative form of SRF led to a severe dilated cardiomyopathy." (PMID 23372767, 2013). "Myocardin is a coactivator of serum response factor which specifically expressed in cardiac and smooth muscle cells, and promoter variation of this gene was proposed as a biomarker of cardiac hypertrophy." (PMID 23102236, 2012). "We had previously observed that mild-overexpression of SRF resulted in the onset of cardiac hypertrophy at 6 months of age." (PMID 21303526, 2011). "Altered expression of miRNA occurred at as early as 7 days after birth, long before the onset of cardiac hypertrophy and continued through 6 months of age, suggesting that SRF overexpression is likely the main factor contributing to dysregulation of microRNAs." (PMID 21303526, 2011). "In contrast, transgenic mice that overexpress Hod develop severe cardiac hypertrophy that is mediated by inhibition of SRF-dependent transcriptional activity." (PMID 17181869, 2006). "In cardiomyocytes, SRF regulates genes that are known to be involved in hypertrophy, its overexpression leads to cardiac hypertrophy, it regulates the function of the contractile apparatus, and its deletion in adult cardiomyocytes in vivo leads to dilated cardiomyopathy." (PMID 39609264, 2025). "However, transgenic mice with cardiomyocytes-specific overexpressing human SRF also leads to serious cardiac hypertrophy." (PMID 35185581, 2022). "In addition, SRF expression levels are decreased in subjects with PE-induced cardiac hypertrophy but increased in aortic banding-induced cardiac hypertrophy." (PMID 35185581, 2022). "Since pulmonary (RV) hypertension has numerous parallels with left ventricular pressure overload-induced hypertrophy, the present study may suggest that MuRF1’s regulatory effects on SRF may contribute to the phenotype observed." (PMID 30241514, 2018). "Scavenging of miR-133 by Malat-1 may therefore increase levels of SRF, an important mediator of cardiac hypertrophy." (PMID 26919721, 2016). "However, cardiac MuRF2 did not appear to regulate SRF activity in vivo, when stimulated by known SRF activating pressure overload-induced cardiac hypertrophy, suggesting this regulation is disease context specific." (PMID 26242235, 2015). "Our findings suggest that restoring miR–133 expression in the context of cardiac hypertrophy could help to repress the impact of SRF/CTGF axis on cardiac fibrosis." (PMID 26440278, 2015).
cardiac hypertrophy (continued). "Given the importance of miR-1 and miR-133 in various cardiomyopathy developments, such as cardiac hypertrophy, understanding the precise control of SRF-mediated microRNA gene regulation in the heart will provide an additional perspective for the treatment of SRF dysfunction-mediated cardiomyopathy." (PMID 24058688, 2013). "Regulation by SRF is a common feature of many genes up-regulated during cardiac hypertrophy." (PMID 23437181, 2013). "However, the function of SRF in the regulation of cardiac hypertrophy is self-contradictory." (PMID 35185581, 2022). "In conclusion, our current study demonstrates that cardiac-specific overexpression of SRF leads to altered expression of cardiac miRNAs, especially the down-regulation of miR-1 and miR-133a, and up-regulation of miR-21, the dysregulation of which is known to contribute to cardiac hypertrophy." (PMID 21303526, 2011). "Interestingly, downregulation of miR-1, miR-133a and upregulation of miR-21 occurred by 7 days of age in these mice, long before the onset of cardiac hypertrophy, suggesting that SRF overexpression impacted the expression of microRNAs which contribute to cardiac hypertrophy." (PMID 21303526, 2011). "KLF-15 expresses in cardiomyocytes and cardiac fibroblasts and upregulates post-natally, inhibiting cardiac hypertrophy by preventing myocardin (MYOCD) and serum response factor (SRF) interactions, thus, diminishing atrial natriuretic factor (ANF) and α-skeletal actin (α-SKA) expression." (PMID 36836777, 2023). "Heart-specific over-expression of SRF in transgenic mice leads to the development of cardiac hypertrophy, chamber dilation, and impaired cardiac function, not very dissimilar from what we observe in MHC-CELFΔ mice." (PMID 23437181, 2013). "In addition, HOP has been suggested to recruit HDACs and form complexes with HDAC2 to inhibit SRF activity; this possible recruitment may be a reason for HOP-mediated cardiac hypertrophy." (PMID 35681202, 2022). "A well-known transcription factor in striated muscle biology is SRF, and Calcium/Calmodulin-dependent regulation of SRF via interaction with CaMKIV and histone deacetylase 4 (HDAC4), but not CaMKII, was demonstrated to be involved in the development of cardiac hypertrophy." (PMID 24659967, 2014). "However, the role of SRF in the regulation of microRNA expression and microRNA biogenesis in cardiac hypertrophy has not been well established." (PMID 21303526, 2011).
gastric cancer (19 papers, 2016 to 2025). A primary or metastatic malignant neoplasm involving the stomach. "SRF, serum response factor, is described to, via miR-199a-5p transactivation, inhibit E-cadherin and is therefore linked to gastric cancer metastasis." (PMID 34654826, 2021). "In primary gastric cancers- high SRF correlates with a more invasive cancer phenotype and high SRF acts as an independent risk factor of short disease free survival." (PMID 28249598, 2017). "Importantly, the overexpression of SRF was found associated with poor prognosis and shorter survival rates in patients with gastric carcinoma, bone and prostate malignancies." (PMID 34588926, 2021). "SRF also plays an important role in tumor progression, facilitating invasion and metastasis in gastric cancer." (PMID 37558923, 2023). "SRF mRNA expression was negatively associated with OS, PFS, and PPS of gastric cancer patients (P<0.05)." (PMID 35747809, 2022). "There was also a positive correlation between ING5 and SRF mRNA expression in gastric cancer (P<0.05)." (PMID 35747809, 2022). "According to the bioinformatics findings, the expression of ING5, SRF, and YY1 mRNA was higher in gastric cancer than in normal mucosa, and negatively associated with favorable prognosis of gastric cancer patients." (PMID 35747809, 2022). "Both Xiantao and UALCAN datasets showed higher SRF mRNA expression in gastric cancer than in normal mucosa (P<0.05)." (PMID 35747809, 2022). "ING5, SRF, and YY1 were overexpressed in gastric cancer, (P<0.05), and associated with worse prognosis of gastric cancer patients (P<0.05)." (PMID 35747809, 2022). "It stimulated Rho/MAPK/SRF signaling in human lymphocytes and gastric carcinoma cells, however it exhibited different pattern of downstream signaling in the mentioned cell types." (PMID 34588926, 2021). "Here we showed that SRF promotes gastric cancer (GC) metastasis through stromal fibroblasts in an SDF1-CXCR4-dependent manner." (PMID 27323859, 2016). "The conditioned medium (CM) from CCD18Co fibroblasts stably transfected with the SRF vector (CCD18Co-SRF) significantly enhanced migration of MKN45 gastric cancer cells." (PMID 27323859, 2016). "The results show that the expression of ISGF-3, TBP, MZF1, and SRF is significantly related to the survival of stomach cancer patients (ISGF-3: HR = 0.47, log-rank P = 1.1e-11; TBP: HR = 1.76, log-rank P = 5.5e-11; SRF: HR = 1.76, log-rank P = 5.5e-11; MZF1B: HR = 1.8, log-rank P = 1.7e-11)." (PMID 35712475, 2022). "In gastric cancer cells, either SRF or YY1 silencing decreased ING5 mRNA and protein expression." (PMID 36425530, 2022). "In addition, UALCAN showed higher SRF mRNA expression in gastric cancer than in normal mucosa (P<0.05)." (PMID 35747809, 2022). "Finally, SRF mRNA expression was negatively associated with OS and disease-free survival (DSS) of gastric cancer patients, according to the Xiantao platform (P<0.05)." (PMID 35747809, 2022). "Serum Response Factor (SRF), as a transcription factor, promotes epithelial cell migration and invasion in prostate cancer, gastric cancer, cervical cancer, and hepatocellular carcinoma and is associated with poor prognosis." (PMID 40103267, 2025). "We analyzed the relationship between the expression of ISGF-3, MZF1, SRF, and TBP and the prognosis of stomach cancer patients by the Kaplan–Meier plotter database." (PMID 35712475, 2022). "It was also elucidated that miR-101 suppresses cell invasion and proliferation in gastric cancer by targeting PIM-1 and serum response factor (SRF)." (PMID 36497343, 2022). "In addition, it has been reported that the activated SRF/MYH9 axis induces gastric cancer (GC) invasion and metastasis, which is related to poor outcome." (PMID 33959503, 2021).
gastric cancer (continued). "Chemerin is reported to upregulate the expression of serum response factor (SRF) in lymphocytes and gastric carcinoma cells through Rho/ROCK signaling." (PMID 34588926, 2021). "The depletion of SRF resulted in a decrease in miR-155 RNA levels in SGC-7901 and MGC-803 gastric cancer cells." (PMID 32675943, 2020). "SRF mRNA and protein levels were significantly reduced in SGC-7901 and MGC-803 gastric cancer cells." (PMID 32675943, 2020). "Furthermore, TRIM28 has been found to facilitate gastric cancer cell proliferation by the serum response factor/Indoleamine 2,3-dioxygenase (SRF/IDO1) axis, whereby it regulates IDO1 expression by modulating SRF levels." (PMID 39768197, 2024). "ING5 had positive relationships with SRF and YY1 expression in gastric cancer (P<0.05)." (PMID 35747809, 2022).
heart failure (17 papers, 2012 to 2025). Inability of the heart to pump blood at an adequate rate to meet tissue metabolic requirements. "To investigate the impact of alternative splicing regulation via SRF in heart failure, we compared the inclusion levels of SRF-associated splicing events between the HF and NF groups across multiple clinical subtypes." (PMID 40869995, 2025). "Dimerization of incompetent SRF mutants in the heart caused various structural defects that were evident postpartum and led to death due to cardiomyopathy and heart failure." (PMID 35681202, 2022). "SRF is cleaved by caspase 3, and the cleaved 32-kDa N-terminal SRF protein is a cause of heart failure." (PMID 35681202, 2022). "This elevated SRF activity is associated with maladaptive hypertrophy, where prolonged or excessive hypertrophic signaling leads to cardiomyopathy, fibrosis, and ultimately heart failure." (PMID 40164849, 2025). "Similarly, cardiomyocyte-specific deletion of SRF in the adult heart results in loss of sarcomeric structure and heart failure, which is similar to the phenotype observed in iCIR2KO and iCIRS12KO hearts in the present study." (PMID 36125265, 2022). "Our in silico analysis identified impaired SRF transcriptional activity in iCIR2KO and iCIRS12KO hearts, which provides a potential molecular mechanism accounting for the loss of sarcomere integrity and development of heart failure in both models." (PMID 36125265, 2022). "The upregulation of BNP, a well-established marker of LV cardiac hypertrophy, cardiac stress and heart failure, further supports these findings, suggesting that SRF exacerbates pathological cardiac remodeling." (PMID 40164849, 2025). "MEF-2 and SRF, in particular, are known to play critical roles in pathological hypertrophy and are part of the “fetal gene” response in pressure overload-induced heart failure." (PMID 30241514, 2018). "In contrast, human heart failure was reported to show elevations of a natural dominant-negative form of SRF arising from alternative splicing." (PMID 25221510, 2014). "First, the observation of consistent, disease-specific SRF exon splicing patterns suggests that such isoforms could be utilized as biomarkers to separate heart failure subtypes or to monitor response to treatment with LVADs." (PMID 40869995, 2025). "These subtype-specific splicing signatures show that SRF may be regulated differently in heart failure, contributing to clinical heterogeneity." (PMID 40869995, 2025). "Hence, the authors stated that the truncated isoform of SRF was the key factor in inducing heart failure." (PMID 35681202, 2022). "In addition, SRF-dependent gene expression was modulated during heart failure in human patients as well as rodent models." (PMID 33060801, 2020). "We have shown recently that Nmrk2 levels are strongly induced in the context dilated cardiomyopathy triggered by heart-specific deletion of the SRF transcription factor and that NR-supplemented diet or voluntary wheel running delays the onset of heart failure in this model." (PMID 30283350, 2018). "In addition, a subsequent human heart failure study showed decreases in full-length SRF and elevated expression of a caspase-3-cleaved product of SRF." (PMID 25221510, 2014). "Both HOPX and FHL2 are down-regulated in human heart failure, and may contribute to the dysregulation of SRF-dependent gene expression during pathogenesis." (PMID 23437181, 2013). "Finally, the pathophysiological consequence of the disruption of SRF factor has been demonstrated to contribute to heart failure in both humans and animals." (PMID 24058688, 2013). "Furthermore, CARDINAL and Myocd expression was significantly upregulated during heart failure in mice and humans, suggesting that they regulate the SRF-mediated cardiac gene network critical to proper functioning of the heart and ventricular remodeling due to stress." (PMID 35681202, 2022).